TNF (tumor necrosis factor)
Diseases named in the same sentence as TNF in open-access papers (continued):
Sharing a sentence is not in itself a finding about the gene and the disease.
osteonecrosis (continued). "Furthermore, another study also indicated that oral administration of Ok-PDRN inhibited the expression of IL-1β, matrix metalloproteinase (MMP)-3, and MMP-7, as well as production of inflammatory mediators including COX-2, prostaglandin E2 (PGE2), and TNF-α in an MIA-induced osteonecrosis model." (PMID 34067499, 2021). "Thus, we focused on TNFα rather than SSBT as a potential underlying cause of osteonecrosis seen in the presence of anti-resorptive agents." (PMID 28387378, 2017). "Previous studies have shown that inflammatory cytokines are increased during the development of steroid-induced osteonecrosis, such as IL-1, IL-2, IL-4, IL-6, IL-10, GM-CSF, IFN-γ, and TNF-α." (PMID 28167850, 2017). "More recently, TNF-α was revealed to induce the inhibition of SATB2 and RUNX2 expression through microRNA-31 whereby inhibiting the osteogenic differentiation of BMSCs in ethanol-induced osteonecrosis." (PMID 35505281, 2022). "In addition, TNF-α can reduce the expression of SATB2 and RUNX2 and promote osteogenic differentiation of BMSCs by decreasing microRNA-31 expression in ethanol-induced osteonecrosis." (PMID 35505281, 2022).
Pain (17 papers, 2012 to 2025). An unpleasant sensory and emotional experience associated with actual or potential tissue damage, or described in terms of such damage. "TNFR1 as the major player of TNF-α signaling has been associated with neuropathic pain related depressive-like behavior in animal NP model along with morphological hippocampal alterations such as impaired neurogenesis and reduced neuroplasticity." (PMID 31217010, 2019). "TNF-α, an essential mediator of chronic inflammation, significantly influences peripheral nerve damage and neuropathic pain." (PMID 40951078, 2025). "The most relevant cytokines observed in PTX-induced neuropathic pain are IL-1β, IL-8, and TNF-α, as well as IL-6, IL-4, and IL-10." (PMID 40006070, 2025). "Several studies in animal models of neuropathic pain have demonstrated that TNF-α plays an essential role both in peripheral and central levels of sensitization." (PMID 37629665, 2023). "This study examined the effect of endurance training on the expression of NLRP3, P38 MAPK, TNF-α, and IL-1β genes in the spinal cord of rats with diabetic neuropathic pain." (PMID 35655729, 2022). "Since then, increasing evidence has put forward the roles of TNF-α in the mechanisms of both peripheral and central neuropathic pain." (PMID 35720399, 2022). "Previous studies have reported that microglial activation induces extensive production of proinflammatory cytokines, such as TNF-α, IL-6, and IL-1β, which are involved in the pathogenesis of neuropathic pain." (PMID 32171293, 2020). "The inflammatory mediators such as interleukin-6 (IL-6), interleukin-8 (IL-8), and tumor necrosis factor-α (TNF-α) released from mast cells play important roles in the inflammation and bladder-associated pelvic pain of IC/BPS." (PMID 33133219, 2020). "It is known that serum levels of proinflammatory cytokines such as IL-1β, IL-6, and TNF-α are significantly upregulated during chronic neuropathic pain and anti-inflammatory cytokines such as IL-10 are significantly downregulated during chronic neuropathic pain state." (PMID 30755780, 2019). "Diabetic patients with painful peripheral neuropathy have higher levels of inflammatory markers than subjects without pain, and the elevation of interleukin (IL)-1, IL-6, and tumor necrosis factor α (TNF-α) are correlated with the progression of degenerative changes in the peripheral nerves." (PMID 31295940, 2019). "Of note, it has been reported that TNF-α promotes the activation of NF-κB by SDF-1 that can sustain the production of pro-inflammatory cytokines underlying the development and progression of paclitaxel-induced neuropathic pain." (PMID 31707979, 2019). "In this study, we investigated the mechanism of action of PRP gel on peripheral nerve-derived pain, focusing on tumor necrosis factor-α (TNF-α) and interleukin-6 (IL-6), which have recently attracted attention in acute and chronic neuropathic pain." (PMID 40951078, 2025). "Increased levels of TNF-α, IL-1β, and IL-6 have been observed both in the DRG and SDH in the spinal nerve ligation model of neuropathic pain." (PMID 23365595, 2012). "Besides, proinflammatory cytokines, including tumor necrosis factor-alpha (TNF-α) and interleukin-1 beta (IL-1β), also play a crucial role in VCR-induced neuropathic pain." (PMID 34199936, 2021).
T-cell lymphoma (17 papers, 2004 to 2025). "The risk of T cell NHL was found to be higher in patients receiving simultaneous treatment with TNF-a inhibitors and thiopurines (95% confidence interval, 4.98–354.09; p < 0.0001)." (PMID 37511975, 2023). "In contrast, our results suggest that TNF-α −308 G and LTA +252 A haplotypes increase the risk of NK/T-cell lymphoma." (PMID 26108796, 2015). "In this case-control study, we investigated the association between several genetic variants of immunoregulatory genes (IL-10, TNF/LTA, and CTLA-4) and risk for nasal NK/T-cell lymphoma in a Chinese population." (PMID 26108796, 2015). "A recent detailed analysis of 100 cases of T-cell non-Hodgkin’s lymphoma (NHL) reported to the US FDA disclosed that 68% of the cases involved exposure to both a TNF-alpha inhibitor and an immunomodulator." (PMID 25174953, 2014). "Young males are at greatest risk of developing the admittedly rare but almost universally fatal hepato-splenic T cell lymphoma when on anti-tumor necrosis factor-α therapy (anti-TNFα) and/or thiopurines such as azathioprine." (PMID 24275852, 2013). "Our study also shows that the TNF/LTA haplotype CGGA (TNF-α -857C/-308G/-238G/LTA +252A) has a 1.5-fold increased risk of NK/T-cell lymphoma compared with those of non-CGGA types." (PMID 26108796, 2015). "The study concluded that patients receiving combination therapy (anti-TNF-a and thiopurine) are at an increased risk of developing T cell NHL compared with the less significant increased risk from thiopurine monotherapy, but TNF-a inhibitor monotherapy did not affect patient risk." (PMID 37511975, 2023). "Subsequent in vitro assays prove that ID1 expression or E-protein inhibition directly stimulates NF-κB and its target cytokines, including tumor necrosis factor-α (TNF-α), in both DP T cell lymphoma cell line 16610D9 and thymocytes isolated from Id1 transgenic mice." (PMID 41146039, 2025). "The risk for T-cell non-Hodgkin's lymphoma is higher with the use of TNF-α inhibitors in combination with thiopurines, but not with TNF-α inhibitors alone." (PMID 26904108, 2016). "Risk of T-cell NHL was higher with concomitant use of TNF-alpha inhibitor with thiopurines (95% CI 4.98-354.09; P < 0.0001) and thiopurines alone (95% CI 8.32-945.38; P < 0.0001) but not with TNF-alpha inhibitor use alone (95% CI 0.13-10.61; P = 1.00)." (PMID 25174953, 2014).
Thrombocytosis (17 papers, 2010 to 2024). Increased numbers of platelets in the peripheral blood. "In PMF patients, the elevation of CXCL10 was associated with thrombocytosis and decreased levels of CXCL10 and IL-17 with erythropenia, while in ET patients the low levels of TNF-α was associated with thrombocytosis." (PMID 34084749, 2021). "Anti-TNF-α therapy can reduce the increased platelets more effectively and rapidly than conventional therapy in SpA patients with thrombocytosis." (PMID 36922788, 2023). "The last part of the study demonstrated that anti-TNF-α therapy can reduce the increased platelets more effectively and rapidly than conventional therapy in SpA patients with thrombocytosis." (PMID 36922788, 2023). "The platelet count of patients in the thrombocytosis group treated with anti-TNF-α therapy on week 0, week 6 and week 12 were collected and compared with conventional therapy group." (PMID 36922788, 2023). "Anti-TNF-α therapy can reduce the increased platelets more effectively and rapidly than conventional treatments in SpA patients with thrombocytosis." (PMID 36922788, 2023). "During the acute phase of IgAV, cytokines such as tumor necrosis factor-α, interleukin-6, and interleukin-8 are significantly increased, leading to thrombocytosis and a more severe disease course." (PMID 37020657, 2023). "Altogether, our date indicated that anti-TNF-α therapy can effectively reduce increased platelet counts in SpA patients with thrombocytosis." (PMID 36922788, 2023). "The thrombocytosis-associated network hinted at a synergy between prothrombotic processes, namely IL-17, MAPK, TNF signaling pathways, and cell adhesion molecules." (PMID 36121875, 2022). "The main inflammatory molecules that are active are TNF-α, IL-1 and IL-6, as well as NETs, which partake in the thrombogenesis aspect by inducing thrombocytosis and hyperfibrinogenemia." (PMID 36295093, 2022). "The thrombocytosis-related subnetwork included deregulated molecules from IL-17, TNF, MAPK signaling pathways, and cell adhesion molecules." (PMID 36121875, 2022). "“Inflammaging” is characterized by immunosenescense and thrombocytosis, as well as overproduction of systemic inflammatory cytokines IL-1, TNFα, IL-6, and C-reactive protein (CRP)." (PMID 34502021, 2021). "However, malignant cells trigger the production of myeloid-stimulating cytokines (i.e., interleukin 6, tumor necrosis factor-α, and growth factors) that contribute to thrombocytosis." (PMID 36110962, 2022). "Neoplasms are usually accompanied by thrombocytosis, which may lead to an elevated MPV and hence an increased risk of metastasis and a poor prognosis, as the tumor can produce or stimulate the production of cytokines including interleukins, interferon-, and tumor necrosis factor." (PMID 27154178, 2016). "All of their four patients had elevated levels of interleukin- (IL-) 1β, tumor necrosis factor-α, and IL-6, and they claimed that nonimmunoglobulinemic mediators could be a possible cause for the arterial thrombosis in addition to thrombocytosis and microangiopathic vasculopathy." (PMID 24716013, 2014). "The nomogram incorporating TNF-α with age, PLT count and spleen size presents a noteworthy tool in the preliminary discrimination of MPN patients and those with idiopathic erythrocytosis or thrombocytosis." (PMID 38585007, 2024). "A total of 145 patients with SpA were included in this study, and non-thrombocytosis was identified in 76 patients while thrombocytosis was found in 69 patients, 38 out of the 69 patients received anti-TNF-α therapy." (PMID 36922788, 2023). "His thrombocytosis did not correlate with disease severity but rather with the different treatments that he was exposed to, subsiding only during treatment with anti Tumor Necrosis Factor (TNF)- agents." (PMID 20356400, 2010).
Thrombocytosis (continued). "Integrated TNF-α with age, PLT count and spleen size into nomograms has demonstrated a rapid and convenient preliminary screening tool to assist physicians in efficiently distinguish MPN patients and IE/IT patients among newly onset erythrocytosis or thrombocytosis patients." (PMID 38585007, 2024).
Ventricular arrhythmia (17 papers, 2009 to 2025). "Studies have demonstrated that elevated TNF-α levels correlate with increased risk of ventricular arrhythmias, while IL-6 and IL-1β promote atrial remodeling, which predisposes individuals to AF." (PMID 40901119, 2025). "Perfused hearts from transgenic mice overexpressing TNFα have a prolonged action potential duration and ventricular arrhythmias associated with reduced expression of the potassium channel protein in the cardiomyocytes." (PMID 32751480, 2020). "Notably, TNFα antagonism and IL-1 inhibition are able to normalize the action potential duration and to significantly reduce the risk of fatal ventricular arrhythmias in these types of animal model." (PMID 32751480, 2020). "Moreover, it is frequently reported that overexpression of TNF-α in transgenic animals causes various atrial and ventricular arrhythmias." (PMID 26977143, 2016). "In young people, TNFα levels were elevated in those with ventricular arrhythmias, and it was suggested that TNFα aggravated arrhythmias." (PMID 38256155, 2024). "Cytokines present in the myocardium, including IL-1β, TNF-α, and IL-6, have even resulted in life-threatening ventricular arrhythmias through modulation of potassium and calcium channels." (PMID 33291425, 2020). "Recent evidence suggests that inflammatory factors, mainly TNF-α, contribute to pathophysiology of ventricular arrhythmias." (PMID 26977143, 2016). "Transgenic mice with cardiac-specific overexpression of TNFα develop cardiac dilatation, interstitial infiltrates, abnormal calcium homeostasis, increased apoptosis, extracellular matrix remodeling, ventricular arrhythmias, and early death." (PMID 23704873, 2013). "Then, our animal experiments confirmed that the increased myocardial expression of TNF-α in AMI rats was closely related to the occurrence of ventricular arrhythmias." (PMID 21584281, 2011). "Our preclinical studies found that plasma concentrations of TNF-α rose in AMI patients and was related to the occurrence of ventricular arrhythmias." (PMID 21584281, 2011). "Perfused hearts from transgenic mice overexpressing TNFα exhibited a prolonged APD and re-entrant ventricular arrhythmias; left ventricular myocytes isolated from these animals revealed a robust decrease of Ito and a reduced expression of the corresponding potassium channel protein." (PMID 26798623, 2015).
babesiosis (16 papers, 2014 to 2025). Babesiosis refers to a condition caused by microscopic parasites that infect the red blood cells. "Our data suggest that an impaired cytokine response, including TNFα or LTα, may also contribute to parasite persistence, but more data in humans with babesiosis and polymorphisms that impact TNFα are needed." (PMID 39452729, 2024). "The response of PBMCs from adult cattle during the acute phase of the babesiosis at 10 dpi showed upregulation of the pro-inflammatory cytokines IL-1β, TNFα and IL-18." (PMID 41398915, 2025). "Nuclear factor kappa-light-chain-enhancer of activated B cells (NF-κB) activation drives the release of pro-inflammatory molecules, such as IL-6, TNF-alpha, ICAM-1, and IL-8, previously associated with babesiosis." (PMID 40305281, 2025). "TNF-α appears to be the most important cytokine with a role in oxidative damage of RBCs during canine babesiosis." (PMID 36839438, 2023). "The change in TNF-α concentration in the rN-BmRON2 group was more obvious, indicating that the rN-BmRON2 protein can play an immunoprotective role during Babesia infection." (PMID 33717108, 2021). "In babesiosis caused by B. bovis, the infection involves production of IL-1β, interleukin-12 (IL-12), gamma interferon (IFN-γ) and TNF-α." (PMID 33132601, 2020). "It is probable that TNF-α is involved in the development of hypotension, renal dysfunction and septic shock in canine babesiosis." (PMID 24553975, 2014). "Tumour necrosis factor alpha (TNF-α) is a proinflammatory cytokine that plays a significant role in the pathogenesis of babesiosis and malaria, and influences the severity of these diseases." (PMID 24553975, 2014). "Increase of serum TNF-α concentration has also been observed in human and bovine babesiosis (Shaio and Lin 1998; Kontaş and Salmanoğlu 2006)." (PMID 24553975, 2014). "Our in vivo experiments showed that rBmTLP immunization could reduce the production of inflammatory cytokines IFN-γ and TNF-α in host circulation, thus may inhibit the excessive inflammatory response induced by Babesia infection." (PMID 35252036, 2022). "Our current study suggested that immunization with rBmSP44 elicits IFN-γ, TNF-α, and IL-10 expression and results in a Th1/Th2 mixed humoral and cellular immune response, which may contribute to protect mice from Babesia infection." (PMID 32733477, 2020). "As mentioned in the introduction, TNF-α and IFN-γ play a significant role in the pathogenesis of babesiosis." (PMID 36839438, 2023). "We observed resolution of babesiosis caused by B. microti despite significant increase in plasmatic TNFα level but it was not as high as reported for WA1 strain, which could be attributed to simultaneous increased production of IL-10 and its anti-inflammatory activity." (PMID 29445365, 2018). "It seems probable that in this disease, as in bovine babesiosis, early increased production of IL-18 and IL-12 stimulates the release of IFN-γ and TNF-α, leading to activation of iNOS and NO production, which together with delayed secretion of IL-10 causes oxidative damage to erythrocytes." (PMID 36839438, 2023). "Furthermore, the levels of the inflammatory cytokines IFN-γ and TNF-α in BmTLP immunized mice were much lower than those in PBS control mice, indicating that rBmTLP immunization may inhibit the excessive inflammatory response induced by Babesia infection." (PMID 35252036, 2022).
bacterial vaginosis (16 papers, 2010 to 2025). Infection caused by bacterial overgrowth in the vagina. "The diversity of microbial communities dominated by bacteria associated with bacterial vaginosis leads to an increase in the levels of cytokines, such as IL-8, IL-1a, IL1b, interferon and tumor necrosis factor." (PMID 35359942, 2022). "For instance, the increased preterm birth risk associated with bacterial vaginosis, which is more prevalent in African Americans, is modified by a rare variant in the promoter region of TNF." (PMID 20811627, 2010). "Additionally, women with bacteria associated with bacterial vaginosis, such as Sneathia and Gardnerella vaginalis, exhibited reduced levels of G-CSF and increased levels of IL-9, IL-10, and TNF-α." (PMID 37373695, 2023). "Indeed, bacterial vaginosis has been associated with increased levels of IL-1 beta, IL-6, IL-8, IL-10 and TNF-alpha, RANTES (CCL5), macrophage inflammatory protein (MIP-1 alpha/CCL3) and MIP-1 beta (CCL4) in genital samples." (PMID 21966450, 2011). "For example, IL-1α, IL-1β, and tumor necrosis factor-α, along with bacterial vaginosis, may be associated with genetic polymorphisms in the innate immune Toll-like-receptor (TLR1, TLR 2, TLR 4 and TLR 9) and proinflammatory cytokines (IL-1β, IL-1ra, IL-6, IL-6, CXCL8, and IL-10)." (PMID 35359942, 2022). "Many patients with bacterial vaginosis (vaginitis) show increased levels of inflammatory cytokines, including tumor necrosis factor (TNF)-α." (PMID 40284791, 2025). "HEC-1A cells were incubated separately with TNF-α, IL-1β, IL-6 or IL-8 at concentrations corresponding to the maximum levels of these cytokines determined in the cervicovaginal fluid of bacterial vaginosis patients." (PMID 36145684, 2022). "Accordingly, lavage from women with bacterial vaginosis, an imbalance of naturally occurring bacterial flora, showed increased TNF-α secretion and TLR4 mRNA expression, illustrating the capacity of these flora to trigger immune responses." (PMID 21253014, 2011). "Similarly, numerous studies have demonstrated the occurrence of high levels of cytokines and chemokines, such as IL-1β, TNF-α, IL-6 and IL-8, in vaginal fluids of women with bacterial vaginosis (BV)." (PMID 37375053, 2023). "In contrast, TNF-α, IL-10, and RANTES were down-regulated in bacterial vaginosis in patients where L. crispatus dominated." (PMID 33495564, 2021). "L. Johnsonii could inhibit bacterial vaginosis by inhibiting the expressions of COX-2, iNOS, IL-1β, and TNF-α by regulating NF-κB activation and by killing G. vaginalis." (PMID 36846767, 2023). "In this study, IL-1ß, IL-6 and IL-8 weresignificantly increased in bacterial vaginosis while TNF-α was not." (PMID 21572958, 2011).